METTL1 (methyltransferase 1, tRNA methylguanosine)
Diseases named in the same sentence as METTL1 in open-access papers (continued):
Sharing a sentence is not in itself a finding about the gene and the disease.
glioma (20 papers, 2017 to 2025). A benign or malignant brain and spinal cord tumor that arises from glial cells (astrocytes, oligodendrocytes, ependymal cells). "Survival analysis demonstrates that elevated METTL1 correlates with poor patient prognosis, and both univariate and multivariate Cox regression analyses suggest that METTL1 serves as an independent prognostic risk factor in glioma." (PMID 41562049, 2025). "High METTL1 expression promotes glioma cell proliferation and is associated with common clinical risk factors." (PMID 41562049, 2025). "Elevated levels of METTL1 expression have been linked to increased proliferation of glioma cells and have the potential to impact the mitogen-activated protein kinase (MAPK) signaling pathway." (PMID 39061374, 2024). "More, METTL1 gene rs10877012 was borderline significantly associated with increased glioma risk (adjusted OR = 1.45, 95%CI = 0.95 − 2.21, P = 0.086) under the recessive model." (PMID 36733406, 2023). "Furthermore, high METTL1 expression is associated with poor prognosis and survival of patients with glioma." (PMID 39979979, 2025). "METTL1 overexpression is significantly linked to glioma development and aggressiveness." (PMID 41208200, 2025). "Furthermore, the association between heightened METTL1 expression and unfavorable prognosis indicates its potential as an autonomous risk factor in gliomas, emphasizing its importance in tumorigenesis and resistance to therapies such as temozolomide." (PMID 39061374, 2024). "In the current study, our results support METTL1 as a pediatric glioma susceptibility gene." (PMID 36733406, 2023). "Based on this evidence, it is reasonable to hypothesize that METTL1 expression is intrinsically associated with the risk factors significantly associated with glioma prognosis." (PMID 34838021, 2021). "Moreover, METTL1 expression was associated with common clinical risk factors and was significantly associated with the prognosis and survival of patients with glioma." (PMID 34838021, 2021). "In addition, the analysis of somatic mutation rates, mutation information in each sample, and variation types indicated that the mutation rate of METTL1 was low in patients with glioma." (PMID 34838021, 2021). "Notably, METTL1 expression is generally elevated in patients with IDH wild-type glioma, and IDH mutation is believed to play an important role in early glioma development." (PMID 34838021, 2021). "High METTL1 expression is significantly associated with poor prognosis of patients with glioma and may represent a valuable independent risk factor." (PMID 34838021, 2021). "The present study showed that increased expression of METTL1 is significantly correlated with the prognosis of patients and different clinical risk factors, suggesting that METTL1 may serve as a promising therapeutic target for glioma." (PMID 34838021, 2021). "Hence, a low correlation was found between METTL1 expression and mutation in glioma samples and the mutation rate was only 0.33%." (PMID 34838021, 2021). "Additionally, based on bioinformatic analyses, the probability of occurrence of mutations in METTL1 in glioma was very low; hence, METTL1-mediated m7G methylation may be important for the development of glioma." (PMID 34838021, 2021). "Recent studies indicate that METTL1-mediated m7G modification plays a critical role in promoting glioma cell proliferation, glycolysis, and tumor progression." (PMID 41562049, 2025). "This reduction in PGK1 expression results in slower tumour growth in vivo, underscoring the critical position of METTL1 mediated m7G in glioma." (PMID 41208200, 2025). "In glioma, METTL1 depletion impairs the m7G modification of PGK1 mRNA, leading to a decrease in PGK1 expression, which suppresses both glioma cell glycolysis in vitro." (PMID 41208200, 2025).
glioma (continued). "In line with this, a comprehensive epitranscriptomic overview in glioma further contextualizes m7G regulators—including METTL1/WDR4 and cap‐dependent readers, within signalling networks and clinical relevance." (PMID 41208200, 2025). "Functional assays show that METTL1 knockdown inhibits glioma cell proliferation and glycolysis and slows tumor growth in mouse models." (PMID 41562049, 2025). "METTL1, which is responsible for m7G modification, has been recognized as a potential biomarker for glioma." (PMID 39061374, 2024). "Through mining TCGA datasets, we also noticed that, in glioma, the higher expression level of METTL1 is closely correlated to poorer survival rate." (PMID 39198433, 2024). "As we have identified IGF2BP family as the binding proteins of internal m7G and can promote decay of the target transcripts, we asked if IGF2BPs, especially IGF2BP3, are involved in the regulation of m7G methylation in glioma given the correlation with METTL1." (PMID 39198433, 2024). "Bioinformatics analyses have revealed a correlation between the dysregulation of N7-methylguanosine (m7G) methylation and the progression of glioma, with RNA methyltransferase 1 (METTL1) being identified as a key factor." (PMID 39061374, 2024). "mETTL1 expression is significantly higher in gliomas than in paracancerous tissues in both normal brain tissues and glioma tissues, and the expression of METTL1 rises with the grade of glioma." (PMID 39289775, 2024). "The glioma grade-dependent increase in METTL1 suggests that METTL1 considerably reinforces the growth of tumor cells." (PMID 37710294, 2023). "Expression of METTL1 was augmented in glioma in comparison to normal tissue, and its expression levels were inversely associated with prognosis in glioma." (PMID 36733406, 2023). "METTL1 is overexpressed in glioma as compared with adjacent normal tissues and increases with increasing tumor grades." (PMID 35590385, 2022). "The collected data demonstrated that METTL1 is potentially important in various tumors, especially in glioma." (PMID 34838021, 2021). "The purpose of this study was to analyze the expression and prognosis of METTL1 in glioma, and to explore the potential analysis mechanism." (PMID 34838021, 2021). "METTL1 expression increased with increasing glioma grades and was significantly higher in glioma than in adjacent noncancerous tissues." (PMID 34838021, 2021). "The expression of METTL1 in glioma was further validated using real-time polymerase chain reaction and immunohistochemistry." (PMID 34838021, 2021). "Meanwhile, siRNA was used to knockdown METTL1 in U87 glioma cells, and the resultant effect on glioma proliferation was verified using the Cell Counting Kit 8 (CCK8) assay." (PMID 34838021, 2021). "This study is the first to explore the prognostic value of METTL1 in gliomas and it was found that the expression of METTL1 increases with the grade of glioma." (PMID 34838021, 2021). "Among the m7G writers, METTL1 and WBSCR22, both of which are highly expressed in glioma tissues and promote their proliferation and growth, are closely associated with the prognosis of glioma patients." (PMID 40469294, 2025). "Functional enrichment and pathway analyses further indicate that the oncogenic role of METTL1 in glioma may be related to the MAPK signaling pathway." (PMID 41562049, 2025). "Interestingly, METTL1 is highly expressed in glioma and significantly promotes its growth and proliferation via activation of the MAPK pathway." (PMID 40469294, 2025). "More recent functional studies have shown that METTL1 further drives glioma progression by catalysing m7G modification and stabilizing PGK1 mRNA, a glycolysis‐related enzyme, thereby enhancing glycolytic flux, accelerating cancer cells growth and survival in vivo." (PMID 41208200, 2025).
glioma (continued). "Experimental studies confirm that METTL1 is upregulated in glioma tissues and cell lines." (PMID 41562049, 2025). "More recent functional evidence indicates that METTL1 drives glioma development through m7G‐dependent modification and stabilization of the glycolytic enzyme PGK1 mRNA, which enhances glycolytic activity, promotes cellular proliferation and accelerates tumour growth in vivo." (PMID 41208200, 2025). "Studies have indicated that METTL1‐mediated m7G may activate the MAPK pathway to promote glioma growth and proliferation." (PMID 41208200, 2025). "Aberrant METTL1 expression has been observed across multiple cancer types—including lung, liver, colorectal, gastric, breast, cholangiocarcinoma, esophageal, glioma, head and neck, and thyroid cancers-where it promotes tumor proliferation, metastasis, therapy resistance, and metabolic reprogramming." (PMID 41562049, 2025). "Gene set enrichment analysis and other functional pathways pertinent to the METTL1 significantly related to the MAPK signaling and concluded that a higher expression of METTL1 can foster a higher proliferation rate of glioma cells implicating its prognostic relevance." (PMID 39012280, 2024). "Thus far, only one publication showed the potential implication of m7G methyltransferase complex METTL1/WDR4 in glioma." (PMID 36733406, 2023). "Genome-wide annotation of genetic variation by the Human Genome Project enabled us to evaluate the association between the genetic variants in the METTL1 and WDR4 genes and glioma susceptibility in a three-center case-control study (314 cases vs. 380 controls) with Chinese children of Han ethnicity." (PMID 36733406, 2023). "In vitro experiments revealed that silencing of METTL1 led to retardation of glioma cell growth." (PMID 36733406, 2023). "METTL1 expression is elevated in gliomas and correlates with tumor grade." (PMID 37964279, 2023). "Because METTL1 levels increased with increasing glioma grade, METTL1 expression levels may be able to be used to predict glioma prognosis." (PMID 35721477, 2022). "METTL1 also demonstrates a high level of genomic amplification in glioma." (PMID 35590385, 2022). "METTL1 enhances the proliferation and growth of glioma, which may involve the tumor-related MAPK signaling pathway." (PMID 35590385, 2022). "Finally, using publicly available databases and collected clinical data, METTL1 was shown to be a potential biomarker for glioma that serves as a promising therapeutic target." (PMID 34838021, 2021). "IHC analysis of glioma samples indicated that METTL1 was localized in the nucleus." (PMID 34838021, 2021). "Furthermore, METTL1 expression was found to be significantly higher in glioma than in the adjacent normal tissues." (PMID 34838021, 2021). "The findings of this study show that METTL1 also affects the proliferation process of gliomas." (PMID 34838021, 2021). "Furthermore, results of functional enrichment and pathway analyses indicate that the mechanism of METTL1 in glioma is potentially related to the MAPK signaling pathway." (PMID 34838021, 2021). "In addition, METTL3, which also belongs to the gene family of METTL1, was found to promote cancer progression in gliomas." (PMID 34838021, 2021). "However, the biological behavior, potential mechanism and pathway of METTL1 on glioma need to be further studied." (PMID 34838021, 2021). "Results of the in vitro experiments revealed that METTL1 affects the proliferation of glioma." (PMID 34838021, 2021). "Therefore, we speculated that in addition to its role in tumors, METTL1 expression may be increased in gliomas and may promote the progression of gliomas, thereby affecting the prognosis of patients." (PMID 34838021, 2021).
glioma (continued). "In addition, high expression of METTL1 promotes glioma proliferation and may regulate mitogen-activated protein kinase (MAPK) signaling pathway." (PMID 34838021, 2021). "Furthermore, the expression of METTL1 in different grades of glioma tissues was evaluated by RT-PCR and IHC, which revealed that METTL1 expression was significantly different between normal brain and glioma tissues, and increased with increasing grades of glioma." (PMID 34838021, 2021). "Studies have indicated that METTL1‐mediated m7G methylation activates the MAPK pathway, promoting glioma growth and proliferation." (PMID 41208200, 2025). "The m7G regulator METTL1 is significantly overexpressed and promotes tumorigenesis and development in AML, BC, ESCC, glioma, HCC, HNSCC, ICC, LC, and NPC, and high expression levels of METTL1 often predict poor survival in these patients." (PMID 35590385, 2022). "For example, METTL1 and WDR4 play a strong carcinogenic role in AML, BC, ESCC, glioma, HCC, HNSCC, ICC, LC, and NPC, promoting the malignant phenotype and progression of tumors; however, METTL1 exerts a significant anti-cancer effect in CC." (PMID 35590385, 2022). "We also validated the role of two upregulated and aggressiveness related RBPs (METTL1 and OAS1) in chemoresistance of LN229 glioma cells to temozolomide." (PMID 28035070, 2017). "We also validated the expression pattern of two upregulated (METTL1 and OAS1) and three downregulated genes (KHDRBS2, RANBP17 and ELAVL3) in glioma cell lines using qRT-PCR." (PMID 28035070, 2017). "Bioinformatic analyses reveal that METTL1 expression increases with tumor grade and is significantly higher in glioma tissues compared to adjacent non-tumor tissues." (PMID 41562049, 2025). "In addition to METTL1, TRMT6 and TRMT61 can promote malignant transformation and progression by sustaining tRNA methylation in glioma." (PMID 40469294, 2025). "METTL1 expression continuously increases with increasing glioma grade and was significantly greater in glioma tissues than in adjacent noncancerous tissues." (PMID 39979979, 2025). "Additionally, a comprehensive epitranscriptomic analysis of glioma further contextualizes m7G regulators, including METTL1/WDR4 and cap‐dependent readers, within key signalling networks, highlighting their clinical relevance in glioma progression." (PMID 41208200, 2025). "We performed lentiviral shRNA mediated knockdown of METTL1 and OAS1 in LN229 glioma cells." (PMID 28035070, 2017). "Thus, increased expression of METTL1 and WBSCR22 may be used to determine the prognosis of glioma patients." (PMID 40469294, 2025). "In addition, the results of functional enrichment and pathway analyses indicate that the molecular mechanism by which high METTL1 promotes glioma proliferation is potentially related to the MAPK signalling pathway, and further study of the relationship between METTL1 and this pathway is necessary." (PMID 39979979, 2025). "However, the role of METTL1 in glioma has not been studied to date." (PMID 34838021, 2021).
nasopharyngeal carcinoma (18 papers, 2023 to 2025). A carcinoma arising from the nasopharyngeal epithelium. "METTL1 is highly expressed in nasopharyngeal carcinoma, and METTL1 promotes the proliferation of nasopharyngeal carcinoma cells by upregulating the Wnt/β-catenin signaling pathway." (PMID 39289775, 2024). "In a similar way to nasopharyngeal carcinoma, in lung cancer, the METTL1/WDR4 complex selectively promotes cell cycle related mRNA (including Cyclin D3 and Cyclin E1) translation processes via m7G tRNA codon dependence." (PMID 39019857, 2024). "Similar to this, elevated METTL1/WDR4 expression in nasopharyngeal carcinoma (NPC) encourages both in vitro and in vivo NPC cell proliferation and metastasis." (PMID 38201505, 2023). "In nasopharyngeal carcinoma, METTL1 increases the conversion of EMT through the WNT/β- catenin signaling pathway, leading to chemoresistance to cisplatin and docetaxel in vitro and in vivo." (PMID 37710294, 2023). "In nasopharyngeal carcinoma (NPC), METTL1/WDR4 promotes tumorigenesis via regulation of Wnt/β-catenin, and their upregulation has been associated with poor prognosis." (PMID 37369946, 2023). "METTL1/WDR4 also promoted nasopharyngeal carcinoma (NPC) cell EMT and chemoresistance to docetaxel and cisplatin by mediating the translation efficiencies of mRNAs in the WNT/β-catenin signaling pathway." (PMID 37612540, 2023). "In nasopharyngeal carcinoma (NPC), METTL1 facilitates proliferation and EMT by activating the WNT/β‐catenin signaling pathway." (PMID 39802639, 2025). "Elevated expression of METTL1/WDR4 mediates m7G tRNA modification, activates the WNT/β-catenin pathway, and promotes EMT and chemoresistance to cisplatin and docetaxel in nasopharyngeal carcinoma (NPC) cells." (PMID 41194259, 2025). "Besides, METTL1/WDR4 is significantly upregulated and correlates with poor prognosis in nasopharyngeal carcinoma (NPC)." (PMID 38943267, 2024). "High levels of METTL1-dependent m7G-tRNA codons selectively increase the corresponding mRNA levels, activate the Wnt/β-catenin pathway and promote the EMT process, increase CyclinD1 protein levels in nasopharyngeal carcinoma cells, and promote the proliferation and migration of cancer cells." (PMID 39019857, 2024). "In addition, the expression of the complex formed by METTL1 and WDR4 was significantly increased in nasopharyngeal carcinoma (NPC)." (PMID 38572667, 2024).
head and neck squamous cell carcinoma (15 papers, 2021 to 2025). A squamous cell carcinoma that arises from any of the following anatomic sites: lip and oral cavity, nasal cavity, paranasal sinuses, pharynx, larynx, and salivary glands. "Another investigation showed that METTL1 facilitated the growth of head and neck squamous cell carcinoma (HNSCC) cells by stabilizing Cyclin Dependent Kinase 4 (CDK4) mRNA, a critical regulator of the cell cycle." (PMID 40809384, 2025). "METTL1 knockout markedly reduced the proliferation, migration, and invasive ability of head and neck squamous cell carcinoma cells, and by decreasing the level of m7G tRNA modification inhibited oncogenic gene translation and PI3K/AKT/mTOR signaling pathway." (PMID 39289775, 2024). "In addition, the upregulation of the METTL1/WDR4 complex and m7G levels in tRNA were also shown to promote the development and malignancy of head and neck squamous cell carcinoma (HNSCC) by regulating a subset of oncogenic transcripts, including genes related to the PI3K/AKT/mTOR signalling pathway." (PMID 39723662, 2025).